GRN (granulin precursor)
Description:
Secreted protein that acts as a key regulator of lysosomal function and as a growth factor involved in inflammation, wound healing and cell proliferation. Regulates protein trafficking to lysosomes, and also the activity of lysosomal enzymes. Also facilitates the acidification of lysosomes, causing degradation of mature CTSD by CTSB. In addition, functions as a wound-related growth factor that acts directly on dermal fibroblasts and endothelial cells to promote division, migration and the formation of capillary-like tubule structures (By similarity). Also promotes epithelial cell proliferation by blocking TNF-mediated neutrophil activation preventing release of oxidants and proteases. Moreover, modulates inflammation in neurons by preserving neurons survival, axonal outgrowth and neuronal integrity. [Granulin-4]: Promotes proliferation of the epithelial cell line A431 in culture. [Granulin-3]: Inhibits epithelial cell proliferation and induces epithelial cells to secrete IL-8. [Granulin-7]: Stabilizes CTSD through interaction with CTSD leading to maintain its aspartic-type peptidase activity.
Synonyms: PGRN; GP88; PCDGF; PEPI; CLN11; FTD2; GEP
Tractability: Small molecule: a high-quality ligand is known. Antibody: UniProt places it where antibodies can reach, with high confidence; its Gene Ontology location is reachable by antibodies, with high confidence; UniProt predicts a signal peptide or a membrane-spanning region. PROTAC: ubiquitination databases record sites on it; its protein half-life has been measured; a small molecule that binds it is known.
Chemical probes: Ezeprogind
Gene: Protein-coding gene on chromosome 17 (44,345,108 to 44,353,106, forward strand). Ensembl gene ENSG00000030582.
Subcellular location: Secreted; Lysosome
Subcellular location (Human Protein Atlas): Lysosomes; Endosomes; Predicted to be secreted
Pathways (Reactome):
Immune System: Neutrophil degranulation
Gene Ontology:
Molecular function: protein binding; protein-folding chaperone binding; RNA binding; growth factor activity
Biological process: lysosomal lumen acidification; lysosomal transport; negative regulation of neuron apoptotic process; negative regulation of neutrophil activation; negative regulation of respiratory burst involved in inflammatory response; positive regulation of aspartic-type peptidase activity; positive regulation of cell migration; positive regulation of epithelial cell proliferation; positive regulation of lysosome organization; protein stabilization; astrocyte activation involved in immune response; lysosome organization; microglial cell activation involved in immune response; negative regulation of microglial cell activation; positive regulation of angiogenesis; positive regulation of axon regeneration; positive regulation of defense response to bacterium; positive regulation of endothelial cell migration; positive regulation of inflammatory response to wounding; positive regulation of neuron apoptotic process; positive regulation of protein folding; regulation of inflammatory response; signal transduction; establishment of localization in cell; maintenance of synapse structure; and 5 more
Cellular component: endoplasmic reticulum; endosome; extracellular exosome; extracellular region; Golgi apparatus; late endosome; lysosomal membrane; lysosome; membrane; plasma membrane; azurophil granule lumen; trans-Golgi network; cerebellar climbing fiber to Purkinje cell synapse; vesicle
Genetic constraint (gnomAD): Loss-of-function variants: 30 observed, 68.91 expected, observed/expected ratio (o/e) 0.44, 90% interval 0.32 to 0.59. The upper end of that interval is the gene's LOEUF score, 0.59, which puts it in group 2 of 6, group 1 being the genes least tolerant of losing a copy. Missense variants: 731 observed, 833.88 expected, observed/expected ratio (o/e) 0.88, 90% interval 0.82 to 0.93. Synonymous variants: 327 observed, 324.17 expected, observed/expected ratio (o/e) 1.01, 90% interval 0.92 to 1.11.
Gene-disease validity (ClinGen):
ClinGen rates the evidence that GRN causes each of these diseases.
frontotemporal dementia and/or amyotrophic lateral sclerosis (autosomal dominant): Definitive.
neuronal ceroid lipofuscinosis (autosomal recessive): Definitive.
Homologues: Orthologues: chimpanzee GRN (99% identical), macaque GRN (93% identical), dog GRN (81% identical), rabbit GRN (78% identical), rat Grn (75% identical), mouse Grn (75% identical), pig GRN (71% identical), guinea pig GRN (65% identical), tropical clawed frog grn (41% identical), zebrafish grnb (34% identical).
Diseases named in the same sentence as GRN in open-access papers:
GRN is named in the same sentence as 327 diseases in open-access papers, as found by Europe PMC text mining. Sharing a sentence is not in itself a finding about the gene and the disease. The quoted sentences say what the papers report.
frontotemporal dementia (285 papers, 2006 to 2026). Frontotemporal dementia (FTD) comprises a group of neurodegenerative disorders, characterized by progressive changes in behavior, executive dysfunction and language impairment, as a result of degeneration of the medial prefrontal and frontoinsular cortices. "Mutations in the GRN gene, resulting in PGRN haploinsufficiency, are one of the major causes of frontotemporal lobar degeneration (FTLD) with TDP-43 positive inclusions." (PMID 40528203, 2025). "Progranulin (GRN) mutations, which lower progranulin levels, are linked to frontotemporal dementia (FTD)." (PMID 41585268, 2025). "Heterozygous mutations in GRN, the gene encoding progranulin (PGRN), are among the leading known genetic causes of frontotemporal dementia (FTD), accounting for approximately one-third of genetic FTD cases and 5-10% of all FTD diagnoses." (PMID 40596721, 2025). "For example, research on heterozygous loss‐of‐function mutations in granulin (GRN) associated with frontotemporal lobar degeneration (FTLD) has shown how peripheral immune responses can affect CNS pathology, suggesting potential therapeutic targets for AD." (PMID 39692624, 2025). "Mutations in progranulin (GRN) are associated with frontotemporal dementia, although a Parkinson disease (PD) phenotype is uncommon, especially in young patients." (PMID 40183420, 2025). "Another TV-based enzyme replacement therapy was developed to treat frontotemporal dementia (GRN-FTD) caused by the GRN mutations." (PMID 39206077, 2024). "Loss-of-function mutations in the progranulin (GRN) gene are an autosomal dominant cause of Frontotemporal Dementia (FTD)." (PMID 38840181, 2024). "Critically, deficiencies in GRN have been linked to a range of neurodegenerative diseases including frontotemporal dementia and Alzheimer’s disease." (PMID 38191490, 2024). "GRN, a recognized frontotemporal dementia (FTD) gene, holds associations not only with FTD but also with LOAD." (PMID 38356889, 2024). "Human loss-of-function mutations in the GRN gene are associated with neurodegenerative diseases, including frontotemporal dementia (FTD), neuronal ceroid lipofuscinosis, and Alzheimer’s disease." (PMID 39390556, 2024). "Therapeutic effects of elevated serum PGRN were investigated in GRN gene mutation carrier frontotemporal dementia patients." (PMID 39000486, 2024). "Heterozygous loss-of-function mutations in the GRN gene are a common cause of frontotemporal dementia." (PMID 39185427, 2024). "One of the most notable associations of GRN is with neurodegenerative disorders, particularly frontotemporal dementia (FTD)." (PMID 38255751, 2024). "Heterozygous loss-of-function mutations in the GRN gene are a major cause of hereditary frontotemporal dementia." (PMID 39033178, 2024). "Firstly, in GWASs of clinical frontotemporal dementia, TMEM106B variants achieved only modest p-values and odds ratios for the behavioral subtype of frontotemporal dementia, and the associations were dependent on GRN mutations." (PMID 37131074, 2023). "Frontotemporal dementia, caused by mutations in the GRN gene which encodes the protein progranulin, is an active area of interventional drug trials that are testing multiple strategies to restore progranulin protein deficiency." (PMID 36694576, 2023). "Heterozygous loss-of-function mutations in progranulin (GRN) cause frontotemporal dementia (FTD), a leading cause of early-onset dementia characterized clinically by behavioral, social, and language deficits." (PMID 36781744, 2023). "Loss-of-function (LOF) mutations in GRN gene, which encodes progranulin (PGRN), cause frontotemporal lobar degeneration with TDP-43 inclusions (FTLD-TDP)." (PMID 36978829, 2023). "Mutations in the GRN gene cause inherited frontotemporal dementia (FTD) and have also been linked to other neurodegenerative diseases, including neuronal ceroid lipofuscinosis (NCL), Alzheimer’s disease (AD) and Parkinson’s disease (PD)." (PMID 37974165, 2023).
frontotemporal dementia (continued). "Mutations in the human progranulin (GRN) gene are a leading cause of frontotemporal lobar degeneration (FTLD)." (PMID 36602862, 2023). "A common cause of frontotemporal dementia (FTD) are nonsense mutations in the progranulin (GRN) gene." (PMID 36893203, 2023). "LOF mutations in the GRN gene cause haploinsufficiency with subsequent frontotemporal lobar degeneration (FTLD) and TDP-43 accumulation." (PMID 37958929, 2023). "Recent studies have demonstrated that mutations of the GRN gene are responsible for frontotemporal lobar degeneration, known as FTLD-U." (PMID 37629187, 2023). "Loss-of-function mutations in progranulin (GRN) are a major autosomal dominant cause of frontotemporal dementia (FTD)." (PMID 37118844, 2023). "Mutations in granulin (GRN) have been associated with neurodegenerative diseases, such as frontotemporal lobar degeneration (FTLD) and neuronal ceroid lipofuscinosis (NCL)." (PMID 36009452, 2022). "Accordingly, carriers of autosomal dominant mutations in the genes associated with TAR DNA-binding protein 43 aggregation, such as Chromosome 9 open reading frame 72 (C9orf72) or progranulin (GRN), are at risk of later developing frontotemporal dementia." (PMID 36632182, 2022). "Instead, they were mostly referred to as frontotemporal lobar degeneration (caused by variants in the GRN/CLN11 gene) or a Parkinson-like neurodegenerative syndrome caused by variants in the ATP13A2/CLN12 gene." (PMID 36034292, 2022). "Here we investigated the proteomic signatures of frontal and temporal cortex from brains with frontotemporal dementia due to GRN and MAPT mutations to identify the key cell types and molecular pathways in their pathophysiology." (PMID 35799292, 2022). "The PGRN gene (GRN) mutation is one of the major genetic causes of frontotemporal lobar degeneration-TAR DNA-binding protein (FTLD-TDP)." (PMID 35085262, 2022). "Haplo-insufficiency of the protein, due to heterozygous mutations in the GRN gene, is a leading cause of frontotemporal lobar degeneration with TDP-43 aggregates (FTLD-TDP)." (PMID 35120524, 2022). "Numerous studies have shown that down-regulation of GRN expression is associated with inflammation in multiple neurodegenerative diseases such as amyotrophic lateral sclerosis, frontotemporal dementia, Alzheimer's disease and Parkinson's disease." (PMID 36203997, 2022). "GRN, one of the causative genes of frontotemporal dementia, is known to be regulated downstream of PARK7 in the context of neuroprotection." (PMID 35910227, 2022). "Diagnosis of schizophrenia and bipolar disorders are common in GRN-mutated frontotemporal dementia patients." (PMID 36160603, 2022). "Heterozygous GRN mutations cause frontotemporal dementia (FTD) with transactive response DNA-binding protein of 43 kD (TDP-43)–positive inclusions." (PMID 33886609, 2021). "In each cell type, we interrogated 11 protein-coding genes (10 genes within a ±500 kb flanking region and GRN, a nearby gene linked to frontotemporal lobar degeneration (FTD), a type of dementia)." (PMID 33637690, 2021). "A single mutation in the human GRN gene resulting in reduced PGRN expression causes types of frontotemporal lobar degeneration resulting in frontotemporal dementia." (PMID 31864418, 2019). "Mutations in the GRN gene can lead to frontotemporal lobar degeneration (FTLD), a cause of dementia, and neuronal ceroid lipofuscinosis (NCL), a lysosomal storage disease." (PMID 30862089, 2019). "Loss-of-function GRN variants are primarily considered to cause frontotemporal lobar degeneration, but there is evidence that missense GRN variants are also linked to the pathogenesis of ALS." (PMID 31475037, 2019). "Loss-of-function GRN mutations are one of the most common genetic causes of frontotemporal dementia (FTD), causing as much as 5–10% of all FTD cases and 20% of familial FTD cases." (PMID 29929528, 2018).
frontotemporal dementia (continued). "We report our comparison of our data with the published clinical and neuropathological characteristics of other GRN mutations as well as other frontotemporal lobar degeneration (FTLD) syndromes, and we present a review of the literature." (PMID 29370838, 2018). "Mutations in progranulin gene (GRN) are associated with familial forms of frontotemporal dementia (FTD)." (PMID 29146050, 2018). "Here, we present a novel GRN mutation resulting in frontotemporal lobar degeneration with a distinct clinical phenotype, and we review reports of GRN mutations associated with familial phenotypic heterogeneity." (PMID 28915852, 2017). "Shortage of progranulin—due to heterozygous null mutations in the progranulin gene (GRN)—is a frequent cause of frontotemporal dementia." (PMID 29249935, 2017). "In 2008, our group described a cluster of families with frontotemporal dementia (FTD) harboring the c.709-1G>A mutation in the progranulin gene (GRN), a mutation unique to individuals in the Basque country." (PMID 28594853, 2017). "Genetic frontotemporal dementia is most commonly caused by mutations in the progranulin (GRN), microtubule-associated protein tau (MAPT) and chromosome 9 open reading frame 72 (C9orf72) genes." (PMID 28529873, 2017). "Mutations in the human GRN gene are one of the most common causes of frontotemporal lobar degeneration (FTLD) and the vast majority cause loss of function by decreasing GRN mRNA and PGRN protein by at least 50 % via haploinsufficiency." (PMID 27341800, 2016). "Progranulin (GRN) loss-of-function mutations leading to progranulin protein (PGRN) haploinsufficiency are prevalent genetic causes of frontotemporal dementia." (PMID 27356620, 2016). "Mutations in the progranulin gene (GRN) are the most common cause of frontotemporal lobar degeneration with TDP-43 inclusions (FTLD-TDP)." (PMID 27138926, 2016). "Loss-of-function mutations in GRN are considered causative for frontotemporal lobar degeneration with ubiquitin-positive inclusions." (PMID 27790088, 2016). "Mutations in the PGRN gene (GRN) are a common cause of frontotemporal lobar degeneration (FTLD) and lead to disease through PGRN haploinsufficiency." (PMID 27341800, 2016). "PGRN has gained much attention with the discovery that haploinsufficiency resulting from the GRN gene mutations can cause frontotemporal lobar degeneration (FTLD), indicating that adequate expression of PGRN is essential for normal CNS aging." (PMID 22509390, 2012). "Progranulin (PGRN), a widely secreted growth factor, is involved in multiple biological functions, and mutations located within the PGRN gene (GRN) are a major cause of frontotemporal lobar degeneration with TDP-43-positive inclusions (FLTD-TDP)." (PMID 22781549, 2012). "GRN mutations cause a progressive neurodegenerative disease, namely frontotemporal lobar degeneration associated with ubiquitin inclusions (FTLD-U)." (PMID 20946666, 2010). "PGRN haploinsufficiency caused by autosomal dominant mutations within the GRN gene leads to progressive neuronal atrophy in the form of frontotemporal lobar degeneration (FTLD)." (PMID 20946666, 2010). "Moreover, frontotemporal lobar degeneration (FTLD) with GRN pathogenic variants experience faster progression of atrophy than C9orf72-FTLD and MAPT-FTLD." (PMID 39920674, 2025). "Loss‐of‐function progranulin (GRN) mutations cause frontotemporal dementia." (PMID 41178544, 2025). "In particular, GRN loss-of-function mutations cause NCL and frontotemporal dementia (FTD)-GRN." (PMID 41387918, 2025). "Haploinsufficiency, often resulting from heterozygous GRN mutations, leads to GRN-associated frontotemporal dementia (GRN-FTD), which accounts for 10–15% of all FTD cases and is characterized by lipofuscinosis, microgliosis, TDP-43 pathology, and cortical neuronal loss." (PMID 40498021, 2025).